MMP8 (matrix metallopeptidase 8)
Diseases named in the same sentence as MMP8 in open-access papers (continued):
Sharing a sentence is not in itself a finding about the gene and the disease.
periodontitis (continued). "MMP8 and MMP13 are generally acknowledged to be the most rewarding salivary biomarkers for the diagnosis of periodontitis, which are crucial proteases that regulate gingival destruction and alveolar bone destruction in periodontitis." (PMID 37261355, 2023). "The high expression of MMP-8 and MMP-9 in chronic periodontitis accurately reflects the patient’s condition and therefore can be used as a biomarker for the diagnosis of periodontitis." (PMID 36923589, 2023). "Matrix metalloproteinase-8 (MMP-8), expressed by neutrophils and macrophages, is a major destructive collagenase involved in periodontitis and caries lesions." (PMID 37308912, 2023). "Our RNA-seq results showed upregulated MMP8 and MMP13 in periodontitis group, which were reported to be involved in the degradation of COL-I, COL-III and extracellular matrix observed in periodontitis." (PMID 37261355, 2023). "The mean differences in MMP8 and MMP9 in the DS group with chronic periodontitis showed highly statistically significant levels compared to both systemically healthy groups." (PMID 37448427, 2023). "This study’s objective was to investigate and compare the levels of MMPs (MMP8 and MMP9) in individuals with DS who have periodontitis (experimental group) to systemically healthy individuals with and without periodontitis (control groups)." (PMID 37448427, 2023). "In this study, we assessed MMP8 (collagenase 2) and MMP9 (gelatinase b) levels in DS individuals with chronic periodontitis to further confirm the release of pro-inflammatory cytokines by specific microorganisms." (PMID 37448427, 2023). "MMP‐8 and MMP‐9 can be detected in GCF collected via intracrevicular washing and can be used as markers for T. denticola growth in periodontitis." (PMID 36414019, 2023). "In the current study, selected salivary biomarkers (MMP-8, MMP-9, and TIMP-1) showed high sensitivity to discriminating periodontitis from periodontal health when used alone or in combination." (PMID 36292174, 2022). "Significant reductions in salivary MMP‐8 concentrations were detected by the biosensor (p = .030) and IFMA (p = .002) in participants with periodontitis 6 months after non‐surgical periodontal treatment." (PMID 35304757, 2022). "This was followed by MMP-8/TIMP-1 (sensitivity of 0.977 and specificity of 1.000), with a cut-off point of 0.464 when comparing control to periodontitis." (PMID 36292174, 2022). "In particular, MMP‐8, MMP‐9, and, to a lesser extent, MMP‐14 have been studied in relation to periodontitis." (PMID 34850390, 2022). "The study results identified a tremendous increase in the levels of MMP-8 and MMP-9, and a decrease in the level of MMP-2, in cases of periodontitis." (PMID 35626325, 2022). "Using ratios of MMP-8 and -9 with TIMP-1 favorably increased the accuracy, with AUCs of 0.986 and 1.000, respectively, to distinguish periodontal health from periodontitis as compared to the level of accuracy when each biomarker was used alone." (PMID 36292174, 2022). "Similarly, a study found that the GCF in the healthy sites of periodontitis patients had elevated inflammatory mediators, including MMP-8, when compared to healthy individuals, suggesting that inflammatory mechanisms may occur before they are clinically diagnosed or symptomatic." (PMID 35268009, 2022). "Salivary levels of miR-1246 in patients with chronic periodontitis were positively correlated with the levels of IL-1β, IL-6, IL-17, TNF-α, MMP-1, MMP-8, TIMP-1, PLI, GI, PD, and AL (P < 0.05)." (PMID 35942384, 2022). "Celecoxib and omega-3 fatty acid treatments reduced gingival expression of MMP-8 and increased MMP-13 expressions in a Sprague-Dawley rat model of periodontitis by lipopolysaccharide." (PMID 36012195, 2022). "The utility and contribution of active MMP-8 (aMMP-8) in the classification of PD and on POC has been assiduously investigated and has impacted periodontitis and peri-implantitis disease classification." (PMID 35453967, 2022).
periodontitis (continued). "One of the currently available and promising biomarkers in saliva is neutrophil collagenase or matrix metalloproteinase 8 (MMP-8), which belongs to a group of collagenases and is considered the most important collagenase in periodontitis." (PMID 35877858, 2022). "In summary, the ROC analyses showed that the AUCs for salivary MMP-8, MMP-9, and TIMP-1 were 0.892, 0.844, and 0.920, respectively, between periodontal health and periodontitis." (PMID 36292174, 2022). "The present study analyzed salivary levels of IL-1β, IL-6, MMP-8, and IL-10 in periodontally healthy subjects and stage III periodontitis individuals." (PMID 35368315, 2022). "Thus, the aMMP-8 PoCT, but not total MMP-8 analysis, is a convenient and practical adjunctive diagnostic tool to monitor the diagnosis treatment and medication as well as maintenance of both periodontitis and peri-implantitis." (PMID 35757444, 2022). "Considering the available immunological data, MMP‐8, IL‐17A, and INF‐γ seem to be promising biomarkers for an interaction between IBD and periodontitis and possible role of Th17 cells deserves further research." (PMID 33690955, 2022). "Based on available evidence, this study aimed to examine the ability of salivary MMP-8, MMP-9, and TIMP-1, individually or in combination, to diagnose periodontitis and to discriminate periodontitis S1 to S3." (PMID 36292174, 2022). "The salivary levels of miR-1246, IL-1β, IL-6, IL-17, TNF-α, MMP-1, MMP-8, and TIMP-1 and the periodontal indexes PLI, GI, PD, and AL in the chronic periodontitis group were significantly higher than those in the healthy control (P < 0.05)." (PMID 35942384, 2022). "Recently, a study was conducted to assess the ability of MMP‐8 biosensor, IFMA, and ELISA immunoassays to differentiate between periodontal health, gingivitis, and periodontitis." (PMID 35769040, 2022). "The mean concentrations of MMP-8 and MMP-9 in the saliva from the periodontitis subjects were, respectively, 2.8 and 4.0 times higher than those in the saliva from the healthy subjects." (PMID 35048079, 2021). "We propose that both active and total MMP-8 show potential for periodontal site screening; however, active MMP-8, determined by IFMA, is more accurate for periodontitis diagnosis." (PMID 34441437, 2021). "Salivary and systemic levels of MMP8 appear to be valuable biomarkers for both acute coronary syndrome (ACS) and periodontitis." (PMID 33916672, 2021). "MMP-8 and MMP-9 have been frequently found to be elevated in chronic or advanced periodontitis, assessing the potential of these MMPs as the most promising periodontitis biomarkers." (PMID 33477537, 2021). "They reported significantly elevated levels of MMP-8 and MMP-9 in saliva from the periodontitis subjects compared with saliva from the healthy subjects." (PMID 35048079, 2021). "MMP-8 and MMP-9 were chosen for assessment in this study as they are the most common MMPs in periodontal tissues that indicate periodontitis progression, severity, and treatment response." (PMID 34444764, 2021). "For example, salivary as well as circulating MMP-8 and MMP-9 levels were significantly elevated in periodontitis patients and reduced after periodontal treatment." (PMID 33498206, 2021). "This analysis revealed that the levels of salivary MMP-8 and MMP-9 were significantly higher in the periodontitis subjects." (PMID 35048079, 2021). "There seems to be a significant increase in MMP expression and activity in chronic periodontitis, especially MMP-1, MMP-3, MMP-7, MMP-8, and MMP-9, with minor contributions from MMP-13 and MMP-14." (PMID 32650590, 2020). "Previous studies have demonstrated that MMP-8, MMP-9, lactoferrin, cystatin C, MPO, PAF, cathepsin B, and ICTP can be used to diagnose periodontitis." (PMID 32503210, 2020). "In the saliva of patients with periodontitis, increased concentrations of MMP-2, MMP-8 and MMP-9 were found in comparison to healthy patients." (PMID 33297580, 2020).
periodontitis (continued). "Using a meta-analytical approach, a previous study found that MMP-8, MMP-9, IL-1β, IL-6, and Hb were salivary biomarkers with good capability to detect periodontitis in systemically healthy subjects." (PMID 33383828, 2020). "It is possible that assay of oral MMP-8 (in the form of GCF, saliva or oral rinse) has positive predictive value for clinical outcome in periodontitis." (PMID 31363141, 2019). "Among MMPs, neutrophil-derived MMPs (MMP-8 and MMP-9) have been reported to play major roles in tissue destruction in periodontitis." (PMID 30386502, 2018). "Extensive studies have been conducted out on gingival crevicular fluid (GCF) components that might serve as potential diagnostic markers for periodontitis, among which matrix metalloproteinase-8 (MMP-8) has shown to be promising, but there were no studies for individuals in China." (PMID 29587716, 2018). "MMP‐8, MMP‐9, and their metalloproteinase inhibitor‐1 (TIMP‐1) have been particularly investigated as periodontitis markers (Gorska & Nedzi‐Gora, 2006)." (PMID 29744196, 2017). "Mammalian collagenases, particularly MMP-1, MMP-8, and MMP-9, are upregulated in periodontitis, gingivitis, and peri-implant disease." (PMID 28811549, 2017). "Because type I collagen represents the bulk component of periodontal extracellular matrix, special attention has been paid to collagenases—particularly MMP-8 and MMP-13- and gelatinases—MMP-2, and MMP-9- in periodontitis." (PMID 28218665, 2017). "MPO levels repeatedly correlate not only with total MMP-8 levels, but also with its active isoenzyme forms; and both MPO and MMP-8 show high accuracy for specific site-diagnosis of chronic periodontitis versus gingivitis and healthy sites." (PMID 28218665, 2017). "What is more, statistical analysis also revealed that MMP-8 levels in GCF in patients with mild, moderate, and severe periodontitis were statistically higher than those in periodontally healthy subjects (P = 0.0020, P = 0.0003, P = 0.020, resp)." (PMID 28757684, 2017). "MMP-14 can activate MMP-8 and -13 in vitro, as well as MMP-2, and has been correlated in vivo with active MMP-13 in periodontitis sites." (PMID 28218665, 2017). "Collagenase levels of MMP-14, MMP-8, and MMP-13, have been correlated in chronic periodontitis patients, which suggests either a co-operative role and/or the potential settlement of collagenase activation cascades." (PMID 28218665, 2017). "And based on previous studies, dramatically elevated levels of MMP-1, MMP-2, MMP-3, MMP-8, and MMP-9 have been detected in gingival crevicular fluid, peri-implant sulcular fluid, and gingival tissue of periodontitis patients." (PMID 27194818, 2016). "However, none of the previous studies have succeed in associating these MMP-8 variants with smoking and periodontitis risk, indicating smoking status may not exert an effect on the association of these SNPs with periodontitis susceptibility." (PMID 27194818, 2016). "Among them, MMP-8, MMP-9, HGF, lactate dehydrogenase, aspartate aminotransferase, and TIMP-2 are strong or potential biomarkers of periodontitis." (PMID 26389079, 2015). "First threshold cutoff values for each analyte were based upon the population distribution for IL-1ß (≥28 pg/mL), IL-6 (≥5.5 pg/mL), MMP-8 (≥140 ng/mL), and MIP-1α (≥5 pg/mL) and selected to optimize sensitivity for detection of periodontitis." (PMID 26347856, 2015). "Researchers measured the GCF MMP-8 levels in chronic periodontitis patients both active and inactive sites before and after periodontal treatment, and they found decreased GCF MMP-8 levels after periodontal treatment except the active sites." (PMID 24886536, 2014). "It was found that the levels of MMP-8, MMP-9, OPG, and IL-1β declined significantly after treatment in volunteers with moderate to severe periodontitis." (PMID 24944840, 2014).
periodontitis (continued). "Among these biomarkers, matrix metalloproteinase-8 (MMP-8), especially in its active matrix metalloproteinase-8 (aMMP-8) form, has emerged as a critical entity due to its significant role in the pathophysiology of both periodontitis and peri-implantitis." (PMID 39657936, 2025). "It is important not to equate aMMP-8 with MMP-8 in the diagnostics of peri-implantitis and periodontitis." (PMID 39941195, 2025). "A recent systematic review on diagnostic sensitivity and specificity of host‐derived biomarkers, assessing only saliva as a sampling source, concluded that certain salivary biomarkers (IL‐6, MMP‐8, IL1‐beta) can potentially be useful alone or in combination, for the diagnosis of periodontitis." (PMID 39801446, 2025). "aMMP-8 especially, rather than total MMP-8, is related to and reflects clinically progressive periodontitis and peri-implantitis, and aMMP-8 is thus not synonymous with total MMP-8 in periodontitis and peri-implantitis diagnostics." (PMID 40136755, 2025). "Our analysis aimed to distinguish any discernible patterns or trends in MMP-8 and aMMP-8 levels among individuals with periodontitis compared to those without." (PMID 40045958, 2025). "This study aims to comprehensively evaluate and compare the diagnostic performance of salivary biomarkers interleukin-1 beta (IL-1β) and matrix metalloproteinase-8 (MMP-8) in identifying periodontal disease across its various stages, including health, gingivitis, and periodontitis." (PMID 40283051, 2025). "MMP-8 is not activated and fragmented in gingivitis, but it is activated and fragmented in periodontitis." (PMID 38786309, 2024). "In the periodontitis group without diabetes, the level of salivary MMP‐8 is significantly higher than the control group and lower than the group with periodontitis and diabetes." (PMID 38433295, 2024). "In another induced periodontitis in a diabetic rat experiment, Cu reduced the infiltration of PMN and monocytes, the degradation of periodontal collagen fibers—and decreased IL-1β, IL-6, TNF-α MMP-9 and MMP-2, MMP-8 levels." (PMID 38793109, 2024). "And hence, moving ahead, aMMP-8 should not be regarded as synonymous with total MMP-8 in periodontitis diagnosis." (PMID 38786309, 2024). "In addition, in the saliva of people with periodontitis, MMP-8 is found in different forms, i.e., in the active form, bound in complexes, pro-MMP-8 of neutrophilic origin, and mesenchymal origin." (PMID 38473967, 2024). "On the other hand, it is known that the MMP-8′s up-regulator’s IL-1β mRNA and activator MMP-7 mRNA and potential endogenous inhibitor TIMP-1 mRNA can be de novo transcriptionally up-regulated in the diseased periodontitis gingivae." (PMID 38786309, 2024). "In this study, the level of salivary MMP‐8 was significantly higher among patients with periodontitis and diabetes than in patients with periodontitis who did not have diabetes and healthy individuals." (PMID 38433295, 2024). "Finally, there was a significant difference in the levels of aMMP-8, the rate of MMP-8 activity, tMMP-8, MPO, PMN elastase, and TIMP-1 between the base level of (untreated) patients with periodontitis and 13 periodontally and systemically healthy controls." (PMID 39273368, 2024). "Expression of matrix metalloproteinases (MMP-8 and -9) in chronic periodontitis patients with and without diabetes mellitus." (PMID 39109771, 2024). "MMP-8 level is elevated in GCF, and thus, in saliva and mouthrinse in cases of periodontitis." (PMID 39641024, 2024). "Previous studies have revealed that aMMP-8 is not synonymous to total MMP-8 in periodontitis and peri-implantitis oral fluid diagnostics." (PMID 39273368, 2024). "In line with previous studies, the results of the present study showed that the EP group had significantly higher serum levels of IL-6, CRP, MMP-8, and ALP and lower levels of IL-10 than the control group confirming that the experimental model used was able to induce experimental periodontitis." (PMID 38033572, 2023).
periodontitis (continued). "Peri-implantitis is no exception and has elevated levels of MMP-8 and the active form-aMMP-8, which are more intensified in peri-implantitis than periodontitis." (PMID 37232785, 2023). "In this study, MMP-8 levels in serum samples were greatly higher in PCOS patients than those in non-PCOS participants, and yet salivary MMP-8 levels were markedly higher in periodontitis patients than those of non- periodontitis subjects." (PMID 37794378, 2023). "MMP-8 in saliva was similar in composition to its counterpart within the gingival sulcus, and a similar pattern of elevated MMP-8 was observed in the gingival sulcus of peri-implantitis to that observed at the site of periodontitis." (PMID 36875028, 2023). "A Dunn–Bonferroni test showed no significant pairwise differences in total MMP-8 levels between the stages of periodontitis." (PMID 38001886, 2023). "Taken together, these findings suggest that MMP-8 in serum may be positively correlated with PCOS, and those in saliva is indicative of periodontitis." (PMID 37794378, 2023). "So, it is important to keep in mind that we are speaking about the percentual share of different MMP‐8 species in oral rinse samples and their correlations with periodontitis‐related factors, not about absolute quantities of these species." (PMID 37877535, 2023). "During the orthodontic treatment, the MMP-8 levels did not vary when compared with those detected at the post-periodontitis examination." (PMID 36902236, 2023). "Various inflammatory mediators, such as IL-6, IL-17A and MMP-8, are essentially involved in the pathogenesis of both PCOS and periodontitis, and especially, the expression and release of MMP-8 increase significantly during the aggravation of periodontal inflammation and the resultant destruction." (PMID 37794378, 2023). "Active MMP‐8, but not the total or latent form, is related to and predicts the progression of periodontitis due to its catalytic activity in oral fluids." (PMID 35304757, 2022). "The increase in MMP‐8/ TIMP‐1 ratio in these studies was predominantly related to increased salivary MMP‐8 levels in periodontitis patients and not necessarily to decreased TIMP‐1 concentrations in saliva." (PMID 34850390, 2022). "Likewise, the ROC curve showed a statistically significant diagnostic accuracy (sensitivity and specificity) with an AUC of 1.000 (p value = 0.0001) for both the MMP-8/TIMP-1 and MMP-9/TIMP-1 combinations when comparing periodontal health and periodontitis S1." (PMID 36292174, 2022). "Among the studied polymorphisms of CFH, MMP8, and S100A8/S100A9/S100A12 gene region, those located in the CFH gene associated with periodontitis, whereas the ones near S100A9 or in the MMP8 gene did not." (PMID 35315933, 2022). "detected a significant positive correlation between salivary levels of matrix metalloproteinase -8(MMP-8) and soluble UA in the chronic periodontitis group, as well as the positive correlation between C-terminal telopeptide of type I collagen (CTX I) and soluble UA." (PMID 36466813, 2022). "Similarly, these cut-off points of both MMP-8/TIMP-1 and MMP-9/TIMP-1 combinations showed the highest sensitivity and specificity (1.000 each) for differentiation between control and S1 periodontitis." (PMID 36292174, 2022). "A longitudinal study was one of the first to show in vivo, utilizing gingival crevicular fluid samples, the direct role of active MMP‐8, but not latent or total MMP‐8 (tMMP‐8), in the progression of periodontitis." (PMID 34800007, 2022). "Early studies showed that MMP-8 levels were statistically higher in periodontitis patients compared to nondiseased ones." (PMID 35368315, 2022). "However, when comparing the ratios of MMP-8/TIMP-1 and MMP-9/TIMP-1, the results showed significant differences in all periodontitis groups in comparison to the control group." (PMID 36292174, 2022). "Hence, the research identified the fact that MMP-8, MMP-9, and MMP-2 biomarkers can aid in the diagnosis of periodontitis." (PMID 35626325, 2022).